TNF (tumor necrosis factor)
Diseases named in the same sentence as TNF in open-access papers (continued):
Sharing a sentence is not in itself a finding about the gene and the disease.
autoimmune disease (continued). "Due to the crucial role of TNF-α in the pathogenesis of these diseases, TNF-α inhibitors have revolutionized the treatment of autoimmune diseases, demonstrating increased efficacy compared to alternative treatments." (PMID 37664349, 2023). "Tumor necrosis factor-α (TNF-α) is a classic cytokine that can be found in inflammatory reactions, autoimmune diseases, tumor immunity, blood diseases, and even acute respiratory distress syndrome." (PMID 37398678, 2023). "Given the predominant role of TNFα in the pathogenesis of both diseases, anti-TNF monoclonal agents have been established in the therapeutic armamentarium of such autoimmune disorders." (PMID 36833372, 2023). "CD8+ T cells can enhance the appearance and development of autoimmune diseases through dysregulation of inflammatory cytokines IFN‐γ and TNF‐α production." (PMID 37771913, 2023). "Both TNF and VEGF, as well as their receptors, are relevant therapeutic targets in cancer and autoimmune diseases, and several monoclonal antibodies targeting these molecules have been used in the clinics for several years." (PMID 37175117, 2023). "This retrospective cohort study evaluated whether anti-TNFα therapy influences incident tinnitus risk among adults with autoimmune disorders and no baseline tinnitus selected from a US electronic health records database (Eversana; 1 January 2010–27 January 2022)." (PMID 36902722, 2023). "We chose TNF as the stimulant because of the efficacy of anti-TNF therapies for the treatment of JIA, RA and other autoimmune diseases." (PMID 36793127, 2023). "The TNF/TNFR superfamily members, known for their crucial role in immune system function, have been extensively studied in the context of autoimmune diseases, inflammatory diseases, and tumors." (PMID 38149239, 2023). "T helper (Th)-like DN T cells secrete cytokines, including interleukin (IL)-4, IL-17, interferon-γ (IFN-γ) and tumor necrosis factor-α (TNF-α), and play a similar role to CD4+ Th cells in infection and autoimmune disease." (PMID 35222392, 2022). "Th1 cells are involved in the pathogenicity of organ-specific autoimmune diseases and express the cytokines interferon gamma (IFN γ), tumor necrosis factor alpha (TNFα) and interleukin 2 (IL-2) which promote inflammation." (PMID 35392117, 2022). "The TNF signaling pathway has been suggested as a therapeutic target for general CKD, autoimmune diseases, and cancers." (PMID 35387335, 2022). "Moreover, M-sec, a controller of TNT generation, has also been suggested as a possible target to influence mitochondrial transport; TNF-alpha inhibitors, such as those employed for the treatment of autoimmune diseases, may decrease TNT generation, as M-sec is TNF-alpha inducible." (PMID 35158927, 2022). "Recently, several studies have suggested that targeted inhibition of TNF-α (by monoclonal antibodies (anti-TNF-α), such as certolizumab pegol (CZP) and infliximab (IFX), is a standard therapy for autoimmune diseases." (PMID 35455977, 2022). "In Hashimoto thyreoiditis, another IgG-mediated autoimmune disorder, FcRn expression in thyroid epithelial cells was shown to be reduced, and interferon-γ (IFN-γ), tumor necrosis factor-α, and interleukin-4 or -10 treatment diminished FcRn expression." (PMID 35326398, 2022). "Here, the authors use a patient database and scRNA-seq to link autoimmune diseases to benign prostatic hyperplasia (BPH), and demonstrate that prostatic hyperplasia is reduced by TNF blockers in humans and mice." (PMID 35440548, 2022). "Tumor necrosis factor (TNF) is a cytokine that regulates immunity by binding to the cytokine receptor (TNFR), which has a role in treating inflammatory, neoplastic, and autoimmune diseases." (PMID 36620779, 2022). "TNF-a, a member of the TNF superfamily, has promising applications in the pathophysiological progress of autoimmune diseases, such as Crohn’s disease, and the development and application of related drugs." (PMID 35359966, 2022).
autoimmune disease (continued). "However, anti-TNF-α therapies have limitations, including known adverse safety risk, loss of therapeutic efficacy due to drug resistance, and lack of efficacy in numerous autoimmune diseases, including multiple sclerosis." (PMID 33854514, 2021). "Due to the involvement of TNF-α in the pathogenesis of autoimmune diseases, TNF-α inhibitors have been successfully developed and applied in the clinical treatment of autoimmune diseases such as Crohn’s disease (CD) and RA." (PMID 33800290, 2021). "This study supports the opposing effects of TNF alpha on its receptors, TNFR1 and TNFR2, and their implication as a drug target for autoimmune disorders." (PMID 34804701, 2021). "The use of biological therapy, such as anti-Tumor Necrosis Factor (anti-TNF) agents, has dramatically changed the treatment of autoimmune disease, including IBD." (PMID 33429950, 2021). "As a major cytokine of the tumor necrosis factor (TNF) superfamily, it is a protein of interest in treating glioma and autoimmune diseases." (PMID 34298735, 2021). "In addition, a previous study suggested that IL‐6 or TNF‐α‐activated NF‐κB p65 could bind to miR‐34a promoter and up‐regulate its transcription, which could serve as a novel mechanistic and therapeutic insight into autoimmune disease progression." (PMID 34346538, 2021). "Therewithal activated CD8+ T cells can produce very high levels of tumor necrosis factor (TNF) and IFN-γ that can contribute directly and/or indirectly to target cell destruction in autoimmune diseases." (PMID 33843169, 2021). "Th1 cells produce interferon-γ (IFN-γ) and tumor necrosis factor-alpha (TNF-α) and are effective against intracellular bacteria and viruses, but are also involved in autoimmune diseases." (PMID 34220827, 2021). "Targeting TNF-α by monoclonal antibodies (anti-TNF-α) such as infliximab (IFX), adalimumab (ADA), and certolizumab pegol (CZP) have become the standard treatment of autoimmune diseases." (PMID 34025650, 2021). "Some studies of autoimmune diseases have reported that MSC-EVs drive a shift from Th1 toward Th2 cells and rebalances Th1/Th2 cells by downregulating proinflammatory cytokines TNFα and IFNγ and upregulating anti-inflammatory cytokines IL-10 or IL-4." (PMID 34447855, 2021). "For TNF-α, the disparate distributions and binding characteristics to receptors are the pathological foundations for the occurrence and development of intraocular inflammation, which could indicate why systematic autoimmune diseases and uveitis have different responses to anti-TNF-α agents." (PMID 34795583, 2021). "Th1 cells defend against infections and tumors but are also involved in the development of autoimmune diseases (T1DM), producing cytokines such as interferon (INF)-γ, Tumor Necrosis Factor (TNF)-α, and interleukin (IL)-2." (PMID 34071190, 2021). "TNF-α is a well-known proinflammatory agent, therefore biologics blocking TNF-α and related cytokine pathways have been used in various inflammatory and autoimmune diseases." (PMID 35096867, 2021). "Our patients demonstrated elevations of five biomarkers of inflammation (IL-1β, IL-21, TNFα, INFγ, and CD30) that are known to be elevated in autoimmune disorders such as RA and SLE." (PMID 33562074, 2021). "In response to ‘second necrosis’, a mass of pro‐inflammatory factors including TNF‐α, IL‐1β and IFN‐γ can be released that subsequently induce inflammation or lead to the development of autoimmune disease." (PMID 33686740, 2021). "A few molecules such as IL-17, checkpointinhibitors, and tumor necrosis factor-alpha (TNF-α) areuniversal targets for a broad spectrum of cancers andinflammatory and autoimmune diseases." (PMID 31376325, 2020). "Tumor necrosis factor-alpha (TNF-α), an established pro-inflammatory cytokine plays a central role in the induction and progression of several chronic inflammatory and autoimmune diseases." (PMID 30967865, 2019).
autoimmune disease (continued). "BCG, inducing regulatory T cells and eliminating autoreactive T cells through Tumor necrosis factor (TNF) activities, has been proposed as treatment for autoimmune diseases such as type 1 diabetes and multiple sclerosis." (PMID 30923339, 2019). "CD28 is a marker for antigen-induced stimulation; repeated TCR activation and presence of TNF-α and type-1 interferons increases the frequency of CD8+CD28– T cells and indicates a proinflammatory status in autoimmune disease." (PMID 30912766, 2019). "In the present study, we identified a mechanism of hypoxia-mediated potentiation of release of tumor necrosis factor α (TNF-α), a pro-inflammatory cytokine with important roles in both anti-cancer immunity and autoimmune disease." (PMID 30463908, 2018). "Expression of the immunoproteasome is induced by interferon-γ (IFN-γ), tumor necrosis factor (TNF) and bacterial lipopolysaccharide (LPS) under inflammatory conditions, such as infections or autoimmune diseases." (PMID 30301161, 2018). "It has been widely reported in the literature that many cytokine and chemokine genes (e.g., TNF-a, IL-8, CXCL2, CXCL3, CXCL10, LIF, IL-17C and IL-23A) are the basis of autoimmune disorder pathways that are characterized by inflammation." (PMID 28099447, 2017). "The expression of the immunoproteasome is induced by interferon-γ (IFN-γ) and tumor necrosis factor-α (TNF-α) under inflammatory conditions, such as infections and autoimmune diseases in the presence of inflammatory cytokines." (PMID 29194379, 2017). "Thus, the current view is that IL-6, especially in combination with TNFα, is capable of inducing Tcon cells to resist Treg suppression, providing an attractive therapeutic target for reducing inflammation and restoring suppressive balance in autoimmune disease." (PMID 27242798, 2016). "Although a great success has been achieved in the design and development of anti-TNF-α-based therapeutics, TNF-α gene deletion in mice have still shown 20% probability of developing into autoimmune diseases in the animal models." (PMID 27177334, 2016). "The compelling evidence suggesting destructive roles for TNF in MS patients, EAE, in vitro studies, and other autoimmune diseases provided the basis to target TNF to treat MS patients." (PMID 26906225, 2016). "The expression of the immunoproteasome is induced by interferon-γ (IFN-γ) and tumor necrosis factor-α (TNF-α) under inflammatory conditions, such as infections, and autoimmune diseases when inflammatory cytokines are present." (PMID 26636107, 2015). "This study aims to shed light on the immunogenicity of the therapeutic anti-TNF-α-antibody IFX, a widely used drug for the treatment of TNF-α-dependent autoimmune disorders." (PMID 26511203, 2015). "TNF agonism, especially through the TNFR2 receptor in select autoimmune disease eliminates autoreactive T cells and induces beneficial T-regulatory cells." (PMID 26266038, 2015). "Furthermore, chebulanin treatment decreased the expression of the autoimmune disease-related cytokines (TNF-α and IL-6) and enzymes (COX-2 and MMP-3), indicating that the therapeutic mechanism of chebulanin may involve inhibition of inflammatory signaling in the joints of CIA mice." (PMID 26402786, 2015). "Thus, the Th1 response is demonstrated to be particularly involved in the pathogenesis of autoimmune diseases and is associated with expansion of Th1 cells as well as secretion of pro-inflammatory cytokines, including interleukin (IL)-6, IL-12, interferon (IFN)-γ, and tumor necrosis factor (TNF)-α." (PMID 25879741, 2015). "Furthermore, it would be of particular interest to determine whether the increase in serum VIP levels reported with TNF blockers is class-specific or is also observed in autoimmune disorders treated with other biological therapies, such as blockade of interleukin (IL)-6 or IL-12 signaling." (PMID 25711477, 2015).
autoimmune disease (continued). "VentiRx Pharmaceuticals is also developing a TLR8 specific antagonist for the treatment of autoimmune diseases; VTX-763 is a preclinical lead which shows marked inhibition of TLR8-induced NF-κB activation and TNF production in vitro." (PMID 24474949, 2014). "Among the variations already found and consistent with our results is a high TNF-α concentration detected in the plasma from the elderly, which may be related to the development of acute and chronic inflammatory conditions, carcinogenesis, and autoimmune diseases." (PMID 23758797, 2013). "CD40 engagement in both T or B cells leads to the production of cytokines, such as IL-12, IL-2, TNF-α, IFN-α, and CD80, developing an environment which is conducive to autoimmune diseases." (PMID 23533546, 2013). "TNFα inhibitors, such as infliximab and etanercept have been FDA-approved and are being successfully used in the clinic for treatment of several autoimmune disorders." (PMID 24369447, 2013). "As most of the co-stimulatory members of the TNF/TNFR superfamily, TNFSF14 has been studied for its impact on autoimmune disease and transplant rejection." (PMID 23844029, 2013). "Experimental autoimmune uveoretinitis, for example, is a Th1-type autoimmune disease, and the disease is characterized by macrophage and CD4 T-cell infiltration together with high levels of IFN-γ and TNF-α production." (PMID 21738388, 2011). "Cross-regulation between TNF and type I IFN has been postulated to play an important role in autoimmune diseases." (PMID 20096109, 2010). "TNF blockers also have been shown to induce antinuclear antibodies (ANA) and antibodies directed against double stranded (ds) DNA in autoimmune diseases, such as RA, spondyloarthritis (SpA) and systemic lupus erythematosus (SLE)." (PMID 20003451, 2009). "Key inflammatory mediators, such as TNFα or CXCL10, play a dual role in the development of autoimmune disease, depending on the time and location of their expression." (PMID 23675028, 2007). "Therefore, TNF-α blockers have been used to treat HS as well as VKHD and many other autoimmune diseases." (PMID 41142785, 2025). "TNF-α plays a crucial role in the progression of various autoimmune diseases, with a substantial body of literature reporting increased expression of TNF-α in several autoimmune diseases, and it is also involved in the pathogenesis of MG." (PMID 40418396, 2025). "As an autoimmune disorder, celiac disease likely influences PRES through similar inflammatory mechanisms documented in other autoimmune conditions, where endothelial dysfunction occurs through cytokine activation (TNFα, IL‐1, and IFNγ)." (PMID 40114993, 2025). "The interactions with TNF‐α, particularly through hydrogen bonding with ARG 32, indicate its role in suppressing excessive inflammation, making B. ramiflora a valuable natural source for managing autoimmune diseases." (PMID 40417737, 2025). "Rituximab is a monoclonal antibody that selectively targets CD20-expressing B cells, offering a substantial benefit in both autoimmune diseases and B-cell malignancies, especially in patients who have not responded to TNF inhibitors." (PMID 40283434, 2025). "Although only 3 patients developed diabetic retinopathy under anti-TNF treatment, we believe that it should not be overlooked that anti-TNF agents activate different autoimmune disease pathways in addition to their presumed protective effects." (PMID 38842591, 2024). "DN T-cells with T helper (Th)-like properties are capable of secreting cytokines such as interleukin (IL)-4, IL-17, interferon-γ (IFN-γ), and tumor necrosis factor (TNF)-α, thereby assuming a role analogous to that of CD4 Th cells in cases of infection and autoimmune disease." (PMID 39544989, 2024). "Notably, both HLA-I-specific and HLA-II-specific pGenes included known drug targets for autoimmune diseases, infectious diseases, and cancer such as LAG3, PDCD1, TNF, and ACE2 affected by HLA-I; and IL18, TREM2, VSIG4, and TLR1 by HLA-II." (PMID 39085222, 2024).
autoimmune disease (continued). "Since autoimmune diseases are mediated by proinflammatory cytokines (especially TNF-α and IL-1β), which are responsible for dysfunction of the respective target cells effective therapeutic regimes require treatment with a TNF-α antibody." (PMID 39420138, 2024). "Considering that our findings suggest neutrophil involvement in autoimmune diseases, we propose that the therapeutic target of neutrophil effector functions may be beneficial for NIU patients failing anti-TNFα therapy." (PMID 39540857, 2024). "Elevated IL-8, IL-10, IL-1β, and TNF-α levels have been reported in subclinical hypothyroid HT patients, though this study did not assess concurrent autoimmune diseases or the potential adverse metabolic impact of hypothyroidism." (PMID 39518417, 2024). "For example, a meta-analysis on a variety of patients (healthy, septic, and autoimmune disease) across a variety of TNF-α promoter SNPs (−238G/A, −308G/A, and −857C/T) points to the absence of any association between TNF-α promoter SNPs and TNF-α production." (PMID 36835647, 2023). "For the analysis of incident tinnitus among patients with autoimmune disorders at baseline, 13,293 patients with anti-TNFα therapy (Yes-TNFα) and a random sample of 25,000 patients with no anti-TNFα therapy (No-TNFα) were selected." (PMID 36902722, 2023). "The incidence of tinnitus was also compared between patients with autoimmune disorders treated with different types of anti-TNFα therapies—AB or FP—and with patients who did not receive anti-TNFα therapy." (PMID 36902722, 2023). "In addition, the TNF/TNFR pathway plays a prominent role in the pathogenesis of chronic inflammatory diseases and autoimmune disorders." (PMID 36674651, 2023). "Similarly, SP1 and JUN have been shown to function together to induce TNF expression in response to viral infection and SPI1 has been shown to promote IL10 expression —a cytokine often seen to be dysregulated in autoimmune diseases as in PR3+ AAV." (PMID 36768148, 2023). "Recent studies have shown that anti-TNF-α therapy does not increase the occurrence of ILD among patients with autoimmune diseases." (PMID 35163689, 2022). "Thus, TNFα has been studied as a therapeutic target for intractable diseases, and several TNF-α Inhibitors have been approved as therapeutic agents for autoimmune diseases." (PMID 36012469, 2022). "In this study, we considered microarray datasets that assessed the differential gene expression observed between responders and non-responders in autoimmune diseases with anti-TNFα as their main pharmacotherapy." (PMID 35627163, 2022). "In other autoimmune diseases, such as spondyloarthropathy and Behcet’s disease, TLR2 expression is downregulated after infliximab therapy, supporting the role of TLR2 in the response to the anti-TNFα therapy." (PMID 35517818, 2022). "Curcumin and Curcuma longa Extract may regulate inflammatory cells (such as Treg) and inflammatory factors (such as CRP, ESR, TNF-α, TGF-β1, IL-6 level), which may be its mechanism for treating autoimmune diseases." (PMID 35979355, 2022). "In view of its outstanding role in autoimmune diseases, sepsis and fibrosis, it is not surprising that TNF is the target of several approved and widely clinically used biologicals." (PMID 35681583, 2022). "On further adjusted analyses, stratified by the level of expression of specific cytokines in autoimmune diseases, 30-day mortality was reduced in those autoimmune diseases with overexpression of IL-1, IL-6, IL-12, IFN-γ, and TNF-α, as well as in those with reduced expression of IL-4 and IL-10." (PMID 35271683, 2022). "Studies investigating its regulatory role on inflammatory markers such as IL-6, IL-17 and TNF-α, suggest that PGZ may be an effective candidate for autoimmune diseases and inflammatory skin disorders." (PMID 36429011, 2022).